GCG (glucagon)
Diseases named in the same sentence as GCG in open-access papers (continued):
Sharing a sentence is not in itself a finding about the gene and the disease.
Hypoglycemia (continued). "Mini-doses of glucagon were found to be efficacious and safe to treat mild hypoglycemia in adults with type 1 diabetes." (PMID 29342932, 2018). "For instance, the liver glycogen content was found to be essential for the protective effect of glucagon in hypoglycemia." (PMID 29595915, 2018). "If blood glucose falls further, glucagon release during hypoglycemia probably has a redundancy of controlling inputs." (PMID 30146176, 2018). "Systemic fructose infusion amplified glucagon and epinephrine responses to hypoglycemia in healthy subjects and increased epinephrine responses in patients with type 1 diabetes." (PMID 30146176, 2018). "Given concern for nocturnal hypoglycemia, and patient interest in steroid-sparing anti-hypoglycemic regimen, she was also started on overnight continuous subcutaneous glucagon infusion via insulin pump." (PMID 29340167, 2018). "Patients with long QT syndrome due to rare loss-of-function mutations in the human ether-á-go-go-related gene (hERG) have prolonged QT interval, risk of arrhythmias, increased secretion of insulin and incretins and impaired glucagon response to hypoglycemia." (PMID 29548277, 2018). "DPP-4 inhibitors significantly increased the GLP-1 and GIP levels, reduced the glucagon levels during hyperglycemia, and sustained glucagon counterregulation during hypoglycemia in patients with T1DM." (PMID 29507862, 2018). "Intramuscular glucagon or intravenous glucose is preferred for unconscious patients or patients with clinically significant hypoglycemia (glucose alert value of < 54 mg/dL)." (PMID 29527102, 2018). "Vhlh mutant mice exhibit impaired glucose homeostasis including severe hypoglycemia and defective insulin and glucagon secretion." (PMID 30209343, 2018). "Glucagon, the principal hyperglycemic hormone, is secreted from pancreatic islet α cells as part of the counter-regulatory response to hypoglycemia." (PMID 29898400, 2018). "Given efficacy in management of hypoglycemia while awaiting definitive tumor-directed therapy, we submit nighttime subcutaneous glucagon infusion and CGMS are valuable additions to the physician’s armamentarium in managing this condition." (PMID 29340167, 2018). "For glucagon expression, weak positive staining was observed in malaria patients with hypoglycaemia, whereas moderate positive staining was present in the group of P. falciparum malaria patients with BS = 40–120 mg/dl and the hyperglycaemic group." (PMID 29993021, 2018). "ADA reports on the subject consider that severe hypoglycaemia is a condition which requires another person to actively administer carbohydrates, glucagon, or take other corrective actions." (PMID 29685177, 2018). "Successful hypoglycemia-treatment criteria were met for 94% when using a mini-dose of glucagon in comparison to 95% when giving oral glucose tablets." (PMID 29342932, 2018). "The system treats then the detected nocturnal hypoglycaemia throughout safe and automatic injection of glucagon." (PMID 30568801, 2018). "For hypoglycemia prevention during and after exercise, it has been suggested that closed loop systems should include both insulin and glucagon so that they can more closely replicate the hormonal changes that usually take place." (PMID 30524371, 2018). "Its main purpose is to deal with nocturnal hypoglycaemia upon its detection by injecting glucagon, automatically." (PMID 30568801, 2018). "As anticipated, HET and HOM mice demonstrated significantly greater glucagon and epinephrine responses to hypoglycemia compared with WT." (PMID 30146176, 2018). "In fact, the tank should carry the powder and the liquid parts of glucagon separated and mix them together after hypoglycaemia detection and just before performing the injection." (PMID 30568801, 2018). "Normally, hypoglycemia stimulates glucagon-induced upregulation of PEPCK expression and gluconeogenesis through cAMP/PKA signalling." (PMID 29995892, 2018).
Hypoglycemia (continued). "Diabetic hyperglycemia also induces oxidative stress and reduces both activation of VMH GI neurons by decreased glucose and glucagon secretion during hypoglycemia." (PMID 29593556, 2018). "After that, the system detects (in a non-invasive way) the nocturnal hypoglycaemia, the automatic treatment procedure that is mainly materialised by glucagon injection, should get launched." (PMID 30568801, 2018). "A few times in the recent past, her husband found her unresponsive in the middle of the night with hypoglycemia and administered glucagon." (PMID 28748191, 2017). "Investigations in rodents additionally demonstrated that administration of exogenous serotonin increased insulin levels and blunted glucagon secretion in response to hypoglycemia." (PMID 28748177, 2017). "In some patients, a positive glycaemic response (rise in the plasma glucose concentration of >1.5 mmol/L from baseline) following an intramuscular/intravenous injection of glucagon at the time of hypoglycaemia provides supportive evidence." (PMID 29280746, 2017). "Severe hypoglycemia, i.e., hypoglycemia requiring administration of carbohydrates, glucagon, or other resuscitative actions, is a potentially fatal condition." (PMID 28591300, 2017). "Most infected animals showed evidence of an acute hypoglycemia, but also exhibited elevated levels of insulin, glucagon and GLP-1." (PMID 28085952, 2017). "In contrast to this, defective glucagon response in hypoglycemic states exacerbates clinical symptoms of hypoglycemia." (PMID 28426798, 2017). "The addition of glucagon in the dual-hormone (insulin and glucagon) system can further reduce hypoglycaemia but limited data exist so far to quantify the improved safety compared with the single-hormone system with announced physical activity." (PMID 28840263, 2017). "It is known that exercise induces hypoglycemia in T1D due to increased glucose uptake as well as inadequate glucagon secretion and/or hepatic glucagon sensitivity." (PMID 28272368, 2017). "The injection of insulin for hyperglycemia should be cautious in case of hypoglycemia on account of decreased hepatic insulin sensitivity, enhanced peripheral insulin sensitivity and subsequently decreased secretion of glucagon." (PMID 29212278, 2017). "Many patients have chronic autonomic neuropathy with hypoglycemia unawareness and an inadequate glucagon response that make them uniquely prone to severe hypoglycemia." (PMID 28748191, 2017). "In some patients a positive glycaemic response (rise in the plasma glucose concentration of >1.5 mmol/L) following an intramuscular/intravenous injection of glucagon at the time of hypoglycaemia provides supportive evidence." (PMID 28855921, 2017). "The α cells secrete the hormone glucagon to control hypoglycemia, and zinc acts as a signaling molecule for glucagon secretion." (PMID 29218234, 2017). "Severe hypoglycemia, defined as “an event requiring assistance of another person to actively administer carbohydrates, glucagon, or take other corrective actions,” occurs in around 25% of patients with T1DM and contributes to substantial morbidity." (PMID 28293906, 2017). "Some systems use insulin alone, but there are other systems in development that see both insulin and glucagon, more akin to a human pancreas, and theoretically better equipped to deal with problematic hypoglycemia." (PMID 28293906, 2017). "In WT α-cells, glucose regulates glucagon secretion via closure of the KATP channel, and the resulting membrane depolarization leads to reduced activation of P/Q-type VDCCs that mediate the Ca2+ entry responsible for hypoglycemia-induced glucagon secretion." (PMID 28575322, 2017). "Similar hypoglycaemia-like glucose concentrations consequently control glucagon release and the store-operated pathway in α-cells, whereas quite different concentrations control this pathway in β-cells." (PMID 27044660, 2016).
Hypoglycemia (continued). "Short- term measures for avoiding hypoglycemia include corticoid, glucagon, diazoxide and glucose intake." (PMID 27134683, 2016). "Under these conditions ZnT8-overexpressing mice required a significantly higher glucose infusion rate (GIR) to maintain hypoglycaemia compared to control mice, suggesting an impairment in glucagon release." (PMID 27390586, 2016). "The early onset of hypoglycaemia with high PSS increases splanchnic glucagon, thereby increasing hepatic gluconeogenesis." (PMID 27347379, 2016). "It has been reported that endotoxin-induced hypoglycemia is paralleled by an increase in counteregulatory hormones such as glucagon as well as gluconeogenic precursor supply (lactate and gluconeogenic amino acids)." (PMID 27990298, 2016). "Supporting this, iVMH administration of the KATP channel blocker glibenclamide inhibited the secretion of glucagon and adrenaline in response to both systemic hypoglycemia and central glucopenia." (PMID 27189932, 2016). "These impairments first include the inability to decrease insulin and to increase glucagon in response to hypoglycemia." (PMID 26521082, 2016). "Glucagon from the pancreatic α-cells is a major blood glucose-regulating hormone whose most important role is to prevent hypoglycaemia that can be life-threatening due to the brain’s strong dependence on glucose as energy source." (PMID 27044660, 2016). "Children with FPs had severe hypoglycemia at diagnosis and required glucagon infusion more often [odds ratio (OR) (95% confidence intervals) (95% CI) 28.13 (2.6–300.1), p = 0.006] to normalize glucose levels." (PMID 26903946, 2016). "It was demonstrated that in an Scn1B null genetic mouse model, pancreatic glucose-stimulated insulin and glucagon secretion reduced and resulted in severe hypoglycemia." (PMID 27608006, 2016). "Plasma levels of glucagon, the most important hormone involved in achieving recovery of glucose levels following acute hypoglycemia, were similar in WT and KO mice 60 min after insulin injection (time when WT mice had started to normalize their glycemia)." (PMID 27148080, 2016). "Under hypoglycemia, increases in circulating glucagon promote hepatic glucose production in part through the activation of gluconeogenesis pathway by CREB coactivator CRTC2." (PMID 27990298, 2016). "Hypoglycaemia suppresses insulin secretion from β-cells and stimulates glucagon secretion from islet α-cells, normalizing blood glucose levels." (PMID 27044683, 2016). "Plasma glucagon levels were consequently measured prior to the onset of hypoglycaemia and at 120 min." (PMID 27390586, 2016). "One of the most important reactions of AMPK towards hypoglycemia is the counterregulatory hormonal responses through glucagon, epinephrine, and corticosterone." (PMID 27547453, 2016). "At presentation, hypoglycemia was severe enough to require intravenous glucagon infusion treatment in 14 (52%) children." (PMID 26903946, 2016). "There are obviously reasons to doubt that inhibitory β-cell factors mediate glucose regulation of glucagon in hypoglycaemia." (PMID 27044660, 2016). "During hypoglycemia, increases in circulating glucagon trigger CRTC2 dephosphorylation in part by increasing its association with CnA at a consensus PXIXIT motif." (PMID 27990298, 2016). "It was another 30 years before the pancreatic α-cells were identified as being the source of glucagon, with hypoglycaemia demonstrated as triggering the release of this hormone." (PMID 27044683, 2016). "During hypoglycemic clamps, intracerebroventricular catalase increased glucagon and epinephrine responses to hypoglycemia, consistent with perceived lower glucose levels." (PMID 27740870, 2016). "It is worthy of interest that when hepatic glycogen content is low, glucagon response to insulin-induced hypoglycemia is reduced." (PMID 27568179, 2016). "So finally, the defect of an increment in glucagon secretion during hypoglycemia is the result of β-cell failure in advanced T2DM." (PMID 27158818, 2016).
Hypoglycemia (continued). "It will be argued that α-cell-intrinsic processes are most important for regulation of glucagon release during recovery from hypoglycaemia and that paracrine inhibition by somatostatin from the δ-cells shapes pulsatile glucagon release in hyperglycaemia." (PMID 27044660, 2016). "In rats, VMN AMPK knockdown abolished the glucagon response to hypoglycemia, whereas pharmacological activation of AMPK in the VMN improved the response to hypoglycaemia." (PMID 27189932, 2016). "By contrast, increased α-cell ZnT8 levels strongly affect responses to hypoglycaemia, as studied in hyperinsulinaemic clamps, as well as glucagon secretion in response to low glucose both in vivo and in vitro." (PMID 27390586, 2016). "Following antecedent exercise in Arm 2, glucagon responses to stepped hypoglycemia were attenuated only at the 45 mg/dL (P = 0.002), as compared to rest (rest 55 = 85 ± 5 pg/mL, exercise 55 = 71 ± 3 pg/mL, rest 45 = 102 ± 6 pg/mL, exercise 45 = 81 ± 3 pg/mL." (PMID 27597762, 2016). "It is therefore reassuring that some recent studies focus on regulation of glucagon secretion in recovery from hypoglycaemia by studying the 0–7 mM glucose range." (PMID 27044660, 2016). "In healthy people, both the liver (via glucagon) and kidney (via catecholamines) equally contribute to the increase in glucose release into the circulation during counterregulation of hypoglycemia; this is largely achieved by gluconeogenesis." (PMID 26239457, 2015). "For severe hypoglycemia in an unconscious individual in the home setting, the recommended treatment is 1 mg glucagon by injection." (PMID 26502880, 2015). "In our case we have described a patient who was diagnosed with Hodgkin's disease and who developed recurrent hypoglycemia despite the administration of glucagon, repeated 50% dextrose, and even D5 and D10 continuous infusions." (PMID 26839722, 2015). "The higher α-cell sensitivity at low glucose concentrations is consistent with ATP’s involvement in glucose control of glucagon secretion during recovery from hypoglycemia." (PMID 25911612, 2015). "The hypoglycemia responds to exogenous glucagon, since glucagon stimulates glycogen breakdown and gluconeogenesis." (PMID 26316440, 2015). "The objective of these studies was to evaluate in animal models the safety of GNP, a formulation of glucagon for intra-nasal administration intended for the treatment of severe hypoglycemia." (PMID 26502880, 2015). "For example, hypoglycemia increases glucagon levels and triggers whole-body proteolysis, while hyperglycemia increases insulin levels and counteracts the proteolytic effect of glucagon." (PMID 26682277, 2015). "We show that deletion of ZnT8 in a limited subset (∼15%) of α-cells is sufficient to increase glucagon secretion at low glucose concentrations in vitro and in vivo and to improve the response to hypoglycemia." (PMID 26178371, 2015). "HAAF is characterized by lack of suppression of endogenous insulin secretion and failure of glucagon and catecholamine secretion during hypoglycemia." (PMID 26343738, 2015). "In these four patients glucagon was administered s.c. over periods of up to 3.5 months (n = 3) or i.v. as short-term management of hypoglycemia (n = 1)." (PMID 26608306, 2015). "By contrast, glucagon secretion is required in type 1 diabetes to ensure an adequate response to insulin-induced hypoglycemia, and a failure of this process contributes significantly to mortality in the latter disease." (PMID 26178371, 2015). "In contrast, the processes by which glucagon release from α-cells is stimulated in response to hypoglycemia and is inhibited when normal glycemia is reestablished continue to puzzle the scientific community." (PMID 25911612, 2015). "Blood samples taken from these mice showed that, at time 0, KO mice had a lower basal secretion, but at 90 min after the imposition of hypoglycemia, they secreted significantly more glucagon than WT controls." (PMID 26178371, 2015).
Hypoglycemia (continued). "Glucagon nasal powder (GNP), a novel intranasal formulation of glucagon being developed to treat insulin-induced severe hypoglycemia, contains synthetic glucagon (10 % w/w), beta-cyclodextrin, and dodecylphosphocholine." (PMID 26502880, 2015). "The medication most commonly used to control hypoglycemia was diazoxide (84 %) followed by somatostatin analogues (16 %), calcium channel antagonists (4 %) and glucagon (1 %)." (PMID 26608306, 2015). "Hypoglycemia resulted in significantly reduced epinephrine, norepinephrine, glucagon, growth hormone, pancreatic polypeptide, and hepatic glucose production responses in females as compared to males." (PMID 25964778, 2015). "There is an estimated 200.000 people/year that are hospitalised due to severe hypoglycaemia, and only 20% of this number use the glucagon emergency kit." (PMID 25852997, 2015). "Hypoglycemia can be managed in a typical manner by administration of oral glucose, intravenous dextrose or glucagon depending upon the severity." (PMID 24934576, 2014). "The patient was revaluated three months later: other episodes of hypoglycaemia had occurred with one episode of severe hypoglycaemia characterized by seizure and treated with glucagon." (PMID 25214204, 2014). "The glucose counterregulatory response involves detection of declining plasma glucose levels and secretion of several hormones including glucagon, adrenaline, cortisol, and growth hormone (GH) to orchestrate the recovery from hypoglycemia." (PMID 24616659, 2014). "It seems that NTS and DMV neurons constitute the first line of defense against hypoglycemia by mediating the release of glucagon." (PMID 24616659, 2014). "The protective mechanisms against hypoglycemia include suppression of insulin secretion and rise of counterregulatory hormones, especially glucagon and epinephrine." (PMID 25177371, 2014). "On the other hand, Elmquist and colleagues have shown that reduction of VMH glutamatergic drive during hypoglycemia reduces the glucagon response to a greater extent than the adrenaline response." (PMID 24616659, 2014). "Our studies showed that hypoglycemia following hyperglycemia in ferrets produces increases in glucagon and pancreatic polypeptide, similar to that observed in human studies." (PMID 24594704, 2014). "Based on in vitro studies using isolated islets opening KATP channels have been argued either to be necessary for glucagon secretion during hypoglycemia or to be stimulated and suppress glucagon release during hyperglycemia." (PMID 24621811, 2014). "In STZ diabetic rats, blockade of VMH GABA receptors restores the glucagon response to hypoglycemia more effectively than the adrenaline response." (PMID 24616659, 2014). "Atropine reduces basal levels of insulin and glucagon induced by hypoglycemia and intravenous injection of arginine, respectively." (PMID 24616659, 2014). "GLP-1 mediated an increase in circulating glucagon levels at PG levels below 3.5 mM and increased glucose infusion rates during the hypoglycemia study." (PMID 24400077, 2014). "Hypoglycemia induced a rapid diminishment of insulin, as well as a rise in glucagon and pancreatic polypeptide levels." (PMID 24594704, 2014). "Slightly higher glucagon levels during hypoglycemia in the GLP-1 group compared to the control experiments was previously found in studies with the GLP-1 analog exenatide and the DPP-IV inhibitor Vildagliptin." (PMID 23543638, 2013). "Our data show that mice with a Vhlh-deficiency in all pancreatic cells die perinatally due to severe hypoglycemia, which appears to result from a defect in glucagon secretion." (PMID 23977255, 2013). "One result of hypoglycaemia is activation of the sympatho-adrenal system and release of glucagon and catecholamines (such as epinephrine), which stimulate hepatic glucose production and haemodynamic changes in an attempt to supply glucose to the brain." (PMID 24053606, 2013).